IL1B (interleukin 1 beta)
Diseases named in the same sentence as IL1B in open-access papers (continued):
Sharing a sentence is not in itself a finding about the gene and the disease.
Arthritis (continued). "The fact that inflammatory licensed MSCs did not have any deleterious effect on chondrocytes, and maintained beneficial anti-inflammatory effects on IL-1β-stimulated chondrocytes, supports the investigation of inflammatory licensed MSCs for clinical use in diseases, such as arthritis." (PMID 29615127, 2018). "C5a signaling induces the development of Th17 cells, which play a critical role in the development of arthritis through the induction of cytokines such as interleukin-1beta (IL-1β), IL-6, and granulocyte-macrophage colony-stimulating factor (GM-CSF) in macrophages." (PMID 30390695, 2018). "Moreover, AXL plays a protective role in experimental arthritis, possibly by regulating the post-translational activation of IL-1β (manuscript accepted for publication)." (PMID 30335822, 2018). "Whereas TNF and IL-1β share some pro-inflammatory activity in arthritis, the reduction in these cytokines after 30 days of Col V supplementation suggests that this might be an adjunct to therapy for arthritis." (PMID 30059520, 2018). "Consistent with other studies, IL-1β was not detectable in joints of naïve rats, but levels were markedly elevated in diseased joints of PIA rats and joint IL-1β levels correlated with arthritis severity score of the corresponding limb (Pearson r = 0.4923, P = 0.0013)." (PMID 29145473, 2017). "Supporting the anti-inflammatory role of PRL in arthritis, PRL-receptor-null mice exhibited increased joint swelling and higher joint expression of the genes encoding for TNFα, IL-1β, IL-6, IFNγ, IL-17A, IL-21, IL-22, IL-23, and IL-10 when subjected to monoarticular AIA (MAIA)." (PMID 28506283, 2017). "In light of its effects, IL-1β has been widely used to mimic arthritis in in vitro studies." (PMID 28550307, 2017). "However, combination therapy using both MTX and FRA resulted in significant attenuation of arthritis-increased IL-1β mRNA expression in rat spleen." (PMID 29113115, 2017). "In addition, IFNγ knockout mice upregulate IL-1β and accelerate collagen-induced arthritis in a mouse strain resistant to developing arthritis when sensitized with collagen." (PMID 28954232, 2017). "Similarly, a previous study demonstrated that IL-6 knockout mice were only mildly protected from mBSA/IL-1β-induced arthritis." (PMID 28587618, 2017). "This may explain the limited anti-inflammatory effect of tryptase inhibition on mBSA/IL-1β-induced arthritis observed in the present study." (PMID 28587618, 2017). "Additionally, tryptase-like activity was upregulated in the synovial fluid from the knee joint of mice submitted to mBSA/IL-1β-induced arthritis." (PMID 28587618, 2017). "IL-1β plays a central role in the pathogenesis of RA and rodent arthritis." (PMID 29145473, 2017). "In addition, release of LTB4 and IL-1β amplifies arthritis by driving the ongoing recruitment of neutrophils." (PMID 27313578, 2016). "In this study, we first confirmed the therapeutic effects of MSCs on CIA mice, using generally applied quantification methods, including the paw thickness, clinical arthritis score, histological arthritis score, and modulation of proinflammatory cytokines, like IL-1β, IL-6, TNF-α, IL-10 and TGFβ1." (PMID 27354158, 2016). "Studies on gout pathogenesis have demonstrated that a single crystal of sodium urate can change NLRP3 configuration, resulting in NLRP3 activation and release of a large number of proinflammatory cytokines, including IL-1β, which participate in the pathogenesis of arthritis." (PMID 27034595, 2016). "In the present study, we found that IL-1β, a key inflammatory cytokine during arthritis, induces the expression of the angiogenic factor FGF-2 in chondrocytes, and subsequently promotes EPC migration and tube formation through the activation of the IL-1RI/ROS/AMPK/p38/NF-κB signalling pathway." (PMID 26811540, 2016).
Arthritis (continued). "Our findings also suggest that the pro-inflammatory role of IL-22 in the physiopathology of arthritis is dependent on the modulation of IL-1β production in the joint, which may be dependent on ASC." (PMID 26330334, 2015). "NF-κB is a transcription factor that acts as a significant part on the onset of inflammation by modulating the expression of pro-inflammatory cytokine (TNF-α, IL-1β, IL-6 and IL-17) genes involved in immune responses, which are all closely connected with the pathogenesis of arthritis." (PMID 26709520, 2015). "Considering the inhibitory potential of these cytokines on many proinflammatory mediators like IL-17, IL-6 and IL-1β, they may contribute to the observed suppression of arthritis severity." (PMID 26110994, 2015). "IL-17 may also contribute directly to joint damage, because it was shown to act synergistically with TNFα and/or IL-1β to induce cartilage destruction in vitro and in experimental arthritis in vivo." (PMID 25436214, 2014). "As augmented IL-1β signaling contributes to more severe arthritis in IL-1RaKO mice, we investigated whether the suppressive effect of EGCG was associated with inhibition of IL-1β signaling." (PMID 24558360, 2014). "In the AIA model, treatment with anakinra had only marginal effects on the severity of arthritis and mechanical hyperalgesia, which may result from the opposite effects of IL-1β on C- and Aδ-fibers." (PMID 25606597, 2014). "Additionally, Ecd inhibited NF-κB phosphorylation, IκBα degradation, and MMP-3, MMP-9, and COX-2 expression in IL-1β-induced arthritis." (PMID 25313362, 2014). "This is in contrast to arthritis-susceptible B6 IL10−/− mice, where previously published data show that in addition to upregulation in IL-1β, IL-6, Cxcl1 and Cxcl2, IFNγ and Cxcl10 are upregulated 16-fold and 141-fold at 2 weeks, and 22-fold and 189-fold at 4 weeks, respectively." (PMID 24967703, 2014). "However, in our previous study, the resulting effect of dendrimer ABP action in arthritic mice was a dramatic decrease of both IL-1β and IL-6, suggesting a strong in vivo capability to decrease inflammatory cytokines involved in arthritis." (PMID 24745366, 2014). "The CIRBP-dependent regulation of IL-1β and NF-κB could be important in a variety of disease states including autoimmune disorders, arthritis and cancer." (PMID 23437386, 2013). "Similarly, soluble IL-1AcP, generated by alternative splicing, forms a complex with IL-1β and IL-1RII playing a protective role in arthritis and has been pharmacologically exploited." (PMID 23847621, 2013). "Taking the two possible mechanisms together, caspase-1 activation by statins may aggravate arthritis by inducing IL-1β and IL-18." (PMID 22537858, 2012). "IL-1β has also been implicated in both RA and CIA; it is known to have a pro-inflammatory role in CIA which is independent of IL-17 and inhibition with an IL-1 receptor antagonist results in amelioration of arthritis." (PMID 22812502, 2012). "Another possible mechanism by which statins may affect arthritis is through their induction of caspase-1, IL-1β, and IL-18 in monocytes, resulting in increased IFNγ production by T cells." (PMID 22537858, 2012). "Also in agreement with our findings, met-RANTES treatment also reduced TNF-α and IL-1β levels in a rat arthritis model." (PMID 21799885, 2011). "IL-1β is considered to be the principal cartilage-catabolic cytokine in arthritis." (PMID 20307272, 2010). "One may speculate that apoptotic cell infusion by downregulating IL-1β production in responses to inflammatory signals controls Th17 response and subsequent arthritis development." (PMID 19570235, 2009). "Assuming that adiponectin plays a role in the pathogenesis of arthritis as a proinflammatory mediator, we tried to determine how significantly adiponectin contributes to joint inflammation and destruction compared with another proinflammatory cytokine, IL-1β." (PMID 19883500, 2009).
Arthritis (continued). "Moreover, IL-1β has been demonstrated as an important mediator of SCW-induced arthritis by promoting Th17 differentiation." (PMID 19570235, 2009). "Furthermore, IL-1β is localized to the synovial pannus in close proximity to bone and cartilage, and cartilage from arthritis patients exhibits upregulation of IL-1β mRNA as compared with normal cartilage." (PMID 18534016, 2008). "Inhibition of TNFα, IL-1β, and IL-6 production is beneficial in several inflammatory diseases including arthritis and numerous efforts have been devoted in the design of novel therapies aimed at blocking the production and/or the biological effects of these important pro-inflammatory cytokines." (PMID 18493620, 2008). "IL-1β is one of the major cytokines in arthritis driving inflammation and joint destruction." (PMID 16356201, 2006). "BZXD can reduce IL-1β level and relieve the arthritis which might result from regulating the immunity function, suppressing the TNF-α expression or combining with the TNF-α receptor and then interrupt the cytokine net." (PMID 23674954, 2005). "IL-1β mRNA increased sharply by 6 hours after induction of arthritis." (PMID 15899031, 2005). "Moreover, studies involving LPS-induced macrophages and adjuvant-induced arthritis in rats demonstrate that the production of pro-inflammatory cytokines such as IL-6, IL-1β, and TNF-α requires activation through the NF-κB, JAK1-STAT1/3, and MAPK signaling pathways to exert inflammatory effects." (PMID 40170729, 2025). "In this study, we demonstrate that arthritis in mice with myeloid-specific Pggt1b deficiency is driven by unprenylated GTP-bound small RHO family GTPases, which in turn trigger Pyrin (Mefv) inflammasome activation, GSDMD-dependent macrophage pyroptosis, and IL-1β secretion." (PMID 40883609, 2025). "Considering that CPPD arthritis may respond to IL-1β blockade, we administered a sub-cutaneous injection of anakinra 100mg 3 times weekly at the end of each haemodialysis session for 5 consecutive sessions, which resulted in a rapid resolution of the arthritis." (PMID 38756932, 2024). "Notably, overexpression of Saa1 in the liver substantially increased IL-1β–induced arthritis." (PMID 38426494, 2024). "IL-1β is related to the inflammation of synovium, which can affect the normal metabolism of chondrocytes, change the structure and function of osteocytes, promote the apoptosis of chondrocytes and the decomposition of cartilage matrix, and it plays a key role in the pathogenesis of arthritis." (PMID 37637408, 2023). "Moreover, in an adjuvant-induced arthritis model, astrocytes expressing GFAP were increased in number and immunostaining intensity in the spinal cord and were associated with increased levels of cytokines such as IL-1β, IL-6, and TNF." (PMID 36387416, 2022). "The progression of arthritis disease is regulated by several microRNAs (miRNAs), including miR-92a, miR-129-3p, miR-141-3p and miR-199a-5p, while the proinflammatory mediators IL-1β, IL-6, TNF-α and matrix metalloproteinases (MMPs) account for histological changes that occur with arthritis." (PMID 34198264, 2021). "The induction and maintenance of joint pain are associated with intense CXCL1-mediated neutrophil influx and production of hyperalgesic mediators, such as IL-1β, and blockade these mediators have been described to suppressed joint pain and damage in murine model of arthritis." (PMID 33995086, 2021). "Surprisingly, CD-1 mice with Smad7 deficiency developed severe arthritis including severe joint swelling, synovial hyperplasia, cartilage damage, massive infiltration of CD3+ T cells and F4/80+ macrophages, and upregulation of proinflammatory cytokines IL-1β, TNFα, and MCP-1." (PMID 30450102, 2018). "Regarding to the claim of indigenous people for application of this material in the treatment of joint inflammation, the present study was designed to evaluate whether Mummy can revoke the inflammatory responses in chondrocytes stimulated with interleukin 1-β (IL-1β)." (PMID 30023330, 2018).
Arthritis (continued). "Therefore IL-1β serves as a link between inflammation and angiogenesis during arthritis." (PMID 26811540, 2016). "Furthermore, pro-inflammatory cytokines such as Il6 and Il1β were increased at mRNA and protein levels in ΔdblGATA arthritic mice compared with WT controls, suggesting that eosinophils play an important role in determining the severity of arthritis." (PMID 27273006, 2016). "Importantly, K/B × N arthritis clinical severity and inflammatory profile was dependent on IL-1R expression, the essential IL-1R signalling adaptor Myd88, and both the IL-1R ligands, IL-1α and IL-1β." (PMID 25693118, 2015). "However, whether ciclamilast can inhibit IL-1β and IL-6 and protect against arthritis remained unknown." (PMID 26000303, 2015). "Importantly, our findings reveal that a TLR–TRIF–RIPK3–caspase-8 signalling pathway may promote K/B × N arthritis disease persistence by driving IL-1β production via transcriptional induction, and/or cleavage induced activation." (PMID 25693118, 2015). "Thus, IL-23 may have other affects on the development of arthritis such as the induction of IL-1β and IL-6." (PMID 25253467, 2014). "Overall, these results demonstrate that high levels of IL-6/sIL-6R, as those present in joints of patients with arthritis, may contribute to the amplification of the inflammatory response enhancing the production of IL-1β, CXCL8 and CCL2 by SFMCs and by RA synoviocytes." (PMID 25271853, 2014). "In addition, naïve mice lacking one or two HO-1 alleles showed IL-1β levels lower than HO-1+/+ animals and arthritis induction led to a significant increase of this cytokine in HO-1+/− animals." (PMID 23285041, 2012). "Thus, while IL-1β is overexpressed in the spinal cords of animals submitted to experimental arthritis and other chronic pain models, intrathecal administration of IL-1β to healthy animals induces hyperalgesia and allodynia and enhances wind-up activity in dorsal horn neurons." (PMID 19586548, 2009). "In an equine IL-1β-induced carpal synovitis model, CCL2, CCL3, CCL5, and CCL11 were identified as sensitive biomarkers during the early stages of joint inflammation (synovitis), exhibiting temporal variations in their response." (PMID 40496923, 2025). "IL-1β+ monocytes and macrophages have also been observed in inhibitor-induced inflammatory arthritis (ICI-arthritis) that occurred after anti-PD-1 therapy." (PMID 40662950, 2025). "It was observed that even the lowest dosage of 0.125% CLA was sufficient to decrease plasma cytokines (IL-1β, TNF-α, IL-6) and reduce arthritis symptoms (paw swelling and clinical scores) by the end of the 84-day trial." (PMID 40806004, 2025). "Arthritis-related inflammation generates pro-inflammatory cytokines such as TNF-α, IL-6, and interleukin (IL)-1β." (PMID 39458926, 2024). "Irradiation of 0.1 sub-THz alleviated arthritis symptoms and reduced the expression of several pivotal proinflammatory cytokines, including IL-6, TNF-α, IL-1b, and IL-17 in CIA mice." (PMID 38892148, 2024). "For example, certain cytokines such as interleukin-1β (IL-1β), tumor necrosis factor-α (TNF-α), and interleukin-6 (IL-6) have been identified as key regulators in OA development and arthritis inflammation." (PMID 38496843, 2024). "Antibodies targeting IL-19 have prevented arthritis and osteolysis in animal models by diminishing the secretion of pro-inflammatory cytokines, including TNF-α, IL-1β, IL-6, and RANKL." (PMID 39104791, 2024). "In the present study, levels of the representative pro-inflammatory Th1/Th17 cytokines (Il-1b, Tnf-a, Il-6, and Il-17a) in a CIA arthritis model were increased by CIA and reversed by CpdA in an Ffa4 gene-dependent manner." (PMID 38892051, 2024). "The only protective factor among those elicited by IL1β in ASCs is CXCL9, whose terminal peptide was studied as a therapeutic agent to ameliorate joint inflammation in a murine model of arthritis." (PMID 39202038, 2024).
Arthritis (continued). "Acid-activatable curcumin polymer micelles significantly protect joint structures from arthritis by inhibiting TNF-α and IL-1β." (PMID 37938371, 2024). "Here, the severity of IL-1β-induced arthritis was dampened by anti-SAA Ab treatment, which suggests that SAA can be targeted to retard IL-1β–dependent arthritides, including gouty arthritis and collagen-induced arthritis." (PMID 38426494, 2024). "IL‐10 suppresses the production of inflammatory mediators, including IL‐1β and TNF‐α, reducing the intensity of inflammatory reactions and alleviating symptoms and inflammation in arthritis." (PMID 39554315, 2024). "IL‐6, IL‐1β, and TNF‐α cytokine levels, on the other hand, significantly increased in the ankle joint tissue when arthritis was induced in mice (model group) (p < .05)." (PMID 39479687, 2024). "In this model, osteostatin reduced the local production of the pro-inflammatory cytokines IL-1β, IL-6, IL-17, and TNF-α, which are increased in patients with arthritis and enhanced the release of the anti-inflammatory cytokine IL-10." (PMID 38474000, 2024). "The administration of PeaNoc XL as an adjunct to standard therapy resulted in a significant reduction in levels of TNF-α (P<0.01), IL-1β (P<0.001), IL-6 (P<0.01), and CRP (P<0.01) in arthritis patients experiencing joint pain and inflammation." (PMID 37767025, 2023). "Cinnamaldehyde can not only significantly reduce the IL-6 content of inflammatory mediator TNF-α in peripheral mononuclear cells of RA patients, but also inhibit the release of IL-1β and matrix MMP-13 from synovial fibroblasts in arthritis patients." (PMID 37033930, 2023). "At the molecular level, CC plays a critical role in the treatment of arthritis by regulating NF-κB, Wnt1/β-catenin and PI3K/AKT/mTOR signaling pathway, inhibiting the expression of IL-6, IL-1β, MMP-3 and TNF-α." (PMID 37637408, 2023). "We, therefore, examined two independent transgenic mouse arthritis models, the TNFemARE model which is driven by TNF, and the A20myel‐KO model which is driven by IL‐1β." (PMID 37694693, 2023). "YH23537 improved joint histopathologic scores and reduced IL-1β and IL-6 expression in OA joints in MIA-induced arthritis rats." (PMID 37159594, 2023). "In view of other IL-1 cytokines, these results are in marked contrast with the critical role of IL-1β in the development of K/BxN STA, whereas both IL-33 and IL-36 were devoid of any effect in this model of arthritis." (PMID 37415987, 2023). "Previous studies have shown that ozone therapy reduces inflammation as well as IL-1β and TNF-α mRNA levels; ozone decreases oxidative stress in PG/PS-induced arthritis in rats." (PMID 37484853, 2023). "Animal studies have shown that ethanolic extract of pomegranate peel can significantly increase paw withdrawal latency and reduce adverse histological changes and arthritis scores, and reduce serum RF, MDA, IL-1β and TNFα." (PMID 37033930, 2023). "Consistent with the decreases in arthritis score by TAS5315, TAS5315 markedly decreased the levels of TNF-α, IL-1β, and IL-6." (PMID 36821545, 2023). "Curculigoorchioides G. contains curculiglycoside, which improves arthritis symptoms in rats induced by collagen type II (CIA) and reduces levels of inflammatory factors (TNF-α, IL-1β, IL-6, IL-10, IL-12 and IL-17A)." (PMID 37893571, 2023). "Cedrol reduced the paw's thickness by inhibiting the release of inflammatory mediators (IL-1B and TNF-α), indicating its anti-inflammatory potential in CFA-induced arthritis." (PMID 35509836, 2022). "We also observed a concomitant increase in the levels of many cytokines, including IL-1β, IL-6, TNF-α, and IL-1α, in knee homogenates in WT mice after arthritis induction." (PMID 35439173, 2022). "Phlomisoside F (5, 10, and 20 mg/kg, p.o., for 28 days) inhibited the expression of TNF-α, IL-1β, IL-6, COX-2, and 5-lipoxygenase (5-LOX), and increased the expression of IL-10 in complete Freund's adjuvant-induced arthritis male Wistar rats." (PMID 35368757, 2022).